INS (insulin)
Diseases named in the same sentence as INS in open-access papers (continued):
Sharing a sentence is not in itself a finding about the gene and the disease.
type 2 diabetes (continued). "Studies in adults show that dietary proteins stimulate the secretion of insulin, and high protein intake has been related to an increased risk of type 2 diabetes." (PMID 26329684, 2016). "Variants in TCF7L2 gene have been reported to affect insulin secretion and body mass index and to promote type II diabetes." (PMID 27936208, 2016). "Studies exploring the association between serum creatinine and lowered insulin sensitivity and type 2 diabetes are rare." (PMID 28123923, 2016). "The metabolic syndrome comprises an increased risk of type 2 diabetes and hyperlipidemia, which is related to a loss of insulin sensitivity in tissues including adipose tissue, muscle and liver." (PMID 27657020, 2016). "While the hallmark of type 2 diabetes is resistance to the action of insulin, diminished or inappropriate secretion of insulin is universally present in type 2 diabetics." (PMID 27685945, 2016). "In conclusion, risk of all-cause, cardiovascular, and cancer mortality associated with insulin therapy in patients with type 2 diabetes, was significantly lower with detemir and glargine in comparison with NPH use." (PMID 27031113, 2016). "Our present study showed that the low serum amylase levels were associated with impaired insulin secretion and insulin action in type 2 diabetes." (PMID 27606813, 2016). "Our findings that the FINDRISC predicts changes in insulin secretion and insulin sensitivity gives evidence that this risk score reflects both major pathophysiological defects needed for the conversion to type 2 diabetes." (PMID 27851812, 2016). "The results of this trial will inform endocrinologists, obstetricians, family doctors, and other healthcare professionals caring for women with type 2 diabetes in pregnancy, as to the benefits of adding metformin to insulin in this high risk population." (PMID 27435163, 2016). "We have previously reported a possible association between increasing insulin dose and increased all-cause mortality in people with type 2 diabetes treated with insulin monotherapy." (PMID 27152598, 2016). "It has been demonstrated that adiponectin exhibits beneficial effects on glucose homeostasis and low level of adiponectin predicts an increased risk for type 2 diabetes through reducing insulin sensitivity." (PMID 27274905, 2016). "Although it is increasingly accepted that impaired insulin secretion underlies the development of type 2 diabetes (T2D), a disease affecting more than 8% of the adult population worldwide, the mechanisms involved remain poorly understood." (PMID 26584158, 2016). "Type 2 diabetes is associated with whole‐body insulin resistance and reduced pancreatic β‐cell insulin secretion." (PMID 26997627, 2016). "Maternal pregnancy diabetes has been associated with higher risk of offspring adiposity, type 2 diabetes risk and higher fasting glucose and insulin in adolescence." (PMID 27036545, 2016). "The rs7903146-T allele in the transcription factor 7-like 2 (TCF7L2) gene has been associated with impaired pancreatic insulin secretion, enhanced liver glucose production, and an increased risk of type 2 diabetes." (PMID 26914832, 2016). "Patients with type 2 diabetes who require insulin therapy are generally at higher CV risk than those who require oral agents only." (PMID 27188479, 2016). "In type 2 diabetes, telomere length shortening causes aging in islet β cell in advance, resulting in reduction of β cell mass and insulin release." (PMID 27071648, 2016). "In conclusion, our case suggests that liraglutide is a useful treatment for insulin allergy associated with hypereosinophilia and anti-insulin IgG antibodies in patients with type 2 diabetes." (PMID 27456688, 2016). "For this reason, we suggest that clinicians monitor baseline blood glucose levels and perform OGTTs before initiating paliperidone therapy in high-risk patients with type 2 diabetes and type 2 diabetes with residual insulin secretion." (PMID 27478670, 2016).
type 2 diabetes (continued). "Thirty out of 87 patients (34%) were misclassified as having type 2 diabetes; these individuals were severely insulin deficient and had started insulin treatment within 3 years of diagnosis." (PMID 27080317, 2016). "Before addressing the causal factors responsible for altered insulin secretion seen during type 2 diabetes, it is imperative to understand the regulation of β‐cell insulin secretion under normal physiological conditions." (PMID 26997627, 2016). "The Isl1 mutation has been found to be associated with type 2 diabetes, but the mechanism responsible for Isl1 regulation of insulin synthesis and secretion still needs to be elucidated." (PMID 28000708, 2016). "Although the β-cell has the remarkable capacity to compensate for the higher insulin demand, this can eventually lead to β-cell overwork and a consequent loss of β-cell function and survival with manifestation of hyperglycemia and type 2 diabetes (T2D)." (PMID 27617438, 2016). "In this work we investigated the associations of frequency-domain HRV parameters with current and antecedent interstitial glucose fluctuations in insulin-treated type 2 diabetic patients at high cardiovascular risk." (PMID 27066358, 2016). "Type 2 diabetes is associated with impaired nutrient‐regulated anaplerosis and insulin secretion in pancreatic β‐cells." (PMID 26997627, 2016). "Type 2 diabetes (TD2) is caused by acquired resistance to insulin-stimulated glucose uptake by cells combined with inadequate compensatory insulin production to overcome the resistance." (PMID 28231175, 2016). "This group also included other pathways such as the gap, tight and adherens junctions pathways, insulin signaling pathways, and a pathway associated with type II diabetes mellitus." (PMID 27379121, 2016). "A Metabochip study found that seven loci previously associated with type 2 diabetes were associated with insulin clearance." (PMID 27846285, 2016). "Another study highlighted two miRNAs (again miR-140-5p as well as miR-532-5p) linked to type 2 diabetes that change with insulin sensitization." (PMID 27456854, 2016). "Cortisol can influence the regulation of blood glucose by altering the body’s release of insulin and sensitivity to insulin, resulting in an increased risk of type 2 diabetes." (PMID 27513574, 2016). "Metabolic syndrome increases the risk of developing type II diabetes by impeding the critical regulatory influence of insulin on glucose, lipid, and protein metabolism." (PMID 26880906, 2016). "This is corroborated by the findings that chronic inflammatory responses play important roles in the pathogenesis of type 2 diabetes by causing islet dysfunction and insulin resistance in both inflammasome-dependent or -independent manners." (PMID 27904436, 2016). "Further studies are needed to determine the risks and benefits of insulin in type 2 diabetes and the possible benefits associated with the administration of concomitant metformin." (PMID 27152598, 2016). "In contrast, muscle loss, whilst accelerated in type 2 diabetes, is unaffected by insulin treatment, possibly due to IR." (PMID 27610086, 2016). "Epidemiological studies indicate that weight loss, even moderate, can improve insulin sensitivity, improve insulin action, and decrease the risk of developing type 2 diabetes." (PMID 28933404, 2016). "Since the risk to develop reduced insulin secretion and type 2 diabetes for humans on statin treatment is dose-dependent, it is interesting that we find different effects on the insulin secretory machinery at different doses of rosuvastatin." (PMID 26986474, 2016). "First, light-to-moderate alcohol consumption is associated with enhanced insulin sensitivity and reduced type 2 diabetes." (PMID 27385005, 2016). "Insulin has been related to early weight gain, and higher insulin levels in formula-fed infants were found to be associated with higher risk of obesity and type 2 diabetes in later life compared to breast-fed infants." (PMID 26987056, 2016).
type 2 diabetes (continued). "In the treatment of type 2 diabetes, depending on the cause and existing metabolic disorders, insulin, insulin secretagogues or sensitizers are used alone or in combination." (PMID 27071614, 2016). "Two systematic reviews mentioned a −0.9 to −5.6 kg and a −1.5 to −4.9 kg (−3.2 kg on average) weight loss when GLP-1 RA was added to insulin in type 2 diabetes patients." (PMID 26597956, 2016). "On the other hand, Type 2 diabetes is linked to disorders of both insulin secretion and insulin action." (PMID 27478851, 2016). "Type 2 diabetes is a condition in which failure to regulate blood glucose levels by the hormone insulin leads to tissue damage, elevated cardio-metabolic risk, and, in the absence of treatment, increased risk of premature death." (PMID 27458578, 2016). "Epigenetic regulation has been postulated to affect glucose metabolism, insulin sensitivity and the risk of type 2 diabetes." (PMID 27019061, 2016). "They improve insulin sensitivity, decrease fat mass with regional adipose tissue distribution, promote weight loss, and lower blood pressure in patients with type 2 diabetes by blocking glucose reabsorption in the kidney." (PMID 27802313, 2016). "This review therefore also considers new insights in the effects of dietary fatty acids on markers of insulin sensitivity and risk of type II diabetes mellitus (T2DM)." (PMID 27650783, 2016). "The authors suggested that HOMA-IR is a marker of linear growth as well as of adiposity, and that pre-pubertal girls are at higher risk of developing type 2 diabetes early in life because they are intrinsically more insulin resistant than boys." (PMID 27658308, 2016). "Insulin-resistant states such as Type-2 Diabetes (T2D) causes a burden to the pancreas, especially on insulin-secreting β cells, owing to the synthesis and secretion of higher amounts of insulin." (PMID 27736926, 2016). "Disturbances in glucose availability and insulin action have been linked to a variety of metabolic disorders such as obesity, metabolic syndrome, and type 2 diabetes." (PMID 26824606, 2016). "The chronic hyperglycemia and inflammatory cytokines that accompany type 2 diabetes are known to cause β-cells to become resistant to insulin signaling, which is usually required for normal β-cell functioning and survival." (PMID 27242781, 2016). "Impaired insulin secretion appears to constitute an important part of the type 2 diabetes pathogenesis associated with dietary exposure to lipophilic POPs." (PMID 27974137, 2016). "Statins increase the risk of type 2 diabetes and decrease insulin sensitivity and insulin secretion in humans." (PMID 27590905, 2016). "First, we provide a rare description of insulin allergy associated with hypereosinophilia, anti-insulin IgG antibodies, and anti-insulin receptor antibodies in a patient with type 2 diabetes." (PMID 27456688, 2016). "People with type 2 diabetes treated with insulin plus concomitant metformin had a reduced risk of death and MACE compared with people treated with insulin monotherapy." (PMID 27152598, 2016). "One of the major characteristics of type 2 diabetes is relative insulin deficiency (hypoinsulinemia) or decreased response to insulin stimulation (insulin resistance)." (PMID 26770984, 2016). "The increased risk of type 2 diabetes is molecularly based on defects in insulin signaling, insulin secretion, and inflammation." (PMID 27069930, 2016). "In the GetGoal-L- Asia and -S trials type 2 diabetes patients were treated with basal insulin and/or sulfonylurea, both of which are associated with weight gain." (PMID 27252787, 2016). "The current study demonstrated that GLP-1 RA given to obese, insulin-using type 2 diabetes patients resulted in a marked weight loss, improved glycaemic control and considerably reduced daily insulin doses." (PMID 26597956, 2016).
type 2 diabetes (continued). "In humans, heterozygous point mutations in the glucokinase (GK) gene result in reduced enzymatic activity and decreased insulin secretion, causing maturity onset diabetes of the young (MODY) with early-onset and persistent hyperglycemia." (PMID 27774459, 2016). "We further investigated association scores with obesity, type 2 diabetes and glucose-stimulated insulin secretion-related phenotypes in summary-level data from the GIANT, DIAGRAM and MAGIC consortiums." (PMID 29263820, 2016). "In type 2 diabetes, the regular insulin oscillations deteriorate, and prediabetes is associated with loss of the characteristic phase relationship between the insulin and glucagon oscillations." (PMID 25911612, 2015). "Early menarche is associated with lower insulin sensitivity and increased adiposity in young adulthood, potentially increasing the risk of type 2 diabetes and the metabolic syndrome later in life." (PMID 26061526, 2015). "An earlier study of 352 Pima Indians showed that high a WBC count was associated with reduced insulin sensitivity, and predictive for developing type 2 diabetes." (PMID 25915047, 2015). "Currently, the narrow therapeutic arsenal against IR is a substantial challenge for physicians in attempts to reduce the risk of IR and/or type 2 diabetes onset in which tissue insulin response is greatly curtailed." (PMID 26159928, 2015). "Epidemiological studies document a link between type II diabetes and increased risk of developing AD, and brain insulin resistance has been described in patients with mild cognitive impairment or AD and in animal models of AD." (PMID 26161852, 2015). "It has been reported that when the body weight of an individual with impaired insulin secretion increases, the risk of developing type 2 diabetes also increases." (PMID 26215867, 2015). "First, light to moderate alcohol drinking is associated with improved insulin sensitivity and protective for type 2 diabetes." (PMID 25965820, 2015). "The ability to quantify both insulin sensitivity and insulin secretion is essential to improving the understanding of the complex physiology underlying type 2 diabetes." (PMID 25881031, 2015). "Defective insulin secretion by pancreatic beta cells underlies type 2 diabetes mellitus (T2D), a disease that increases globally and soon is estimated to affect >500 million people." (PMID 25803449, 2015). "This discussion of the mechanisms by which obesity and type 2 diabetes promote breast cancer risk and progression focuses on estrogen production and bioactivity and the direct and indirect actions of insulin." (PMID 26516917, 2015). "It has been reported that insulin secretion is reduced by a variant of ADAMTS9 that confers increased type 2 diabetes risks in humans." (PMID 26218657, 2015). "An insulin resistant state is evident in the brain early in AD progression, and a number of epidemiological studies have identified Type-2 diabetes (T2D), in which an insulin resistant state exists, as a risk factor for developing AD." (PMID 26297026, 2015). "More than 50% of women with PCOS are insulin resistant, with an estimated that they have a 5- to 8-fold increased risk of type 2 diabetes mellitus (T2DM) compared with age- and weight-matched controls." (PMID 25595199, 2015). "Due to peripheral insulin resistance associated with type II diabetes, insulin and IAPP expression, maturation, and secretion by pancreatic β-cells are significantly increased." (PMID 26576436, 2015). "As IAPP is coexpressed, copackaged, and cosecreted with insulin by the pancreatic β-cells, the overproduction of insulin often associated with type II diabetes will lead to an increased release of IAPP." (PMID 26576436, 2015). "Apoptosis of β-cells has been demonstrated to be involved in autoimmune T1D and type 2 diabetes (T2D), as in the loss of insulin producing cells after islet transplantation." (PMID 25604067, 2015).
type 2 diabetes (continued). "The main cause of creating hyperglycemia characteristics in type 2 diabetes are genetic and metabolic defects in the performance or secretion of insulin." (PMID 25848640, 2015). "TRB3, a mammalian tribbles homologue, whose chromosomal region 20p13-p12 has been linked to human type 2 diabetes, affects insulin signaling and action by inhibiting Akt phosphorylation, which was also observed in the present study." (PMID 25793876, 2015). "It is critical to recognize early abnormalities of glucose and insulin metabolism in order to prevent progression of type 2 diabetes and cardiovascular comorbidities associated with hyperinsulinemia and glucose intolerance." (PMID 26489022, 2015). "Type II diabetes mellitus (DM) is a chronic metabolic disorder, characterized by relative insulin deficiency due to disorders of insulin secretion and insulin resistance, the prevalence of which has increased continually in the majority of countries." (PMID 26690104, 2015). "It increases the risk of type 2 diabetes by modifying the effect of incretins on insulin secretion, increasing gluconeogenesis and insulin resistance." (PMID 26576435, 2015). "There is insufficient evidence outside clinical trials on the risk of hypoglycemic events in insulin-treated type 2 diabetes patients." (PMID 25698911, 2015). "A genetic variation of ADRA2A (risk A allele for rs553668) is known to cause overexpression of ADRA2A, which aggravates adrenergic suppression of insulin secretion and causes type 2 diabetes." (PMID 25946000, 2015). "It is known that both type 1 and type 2 diabetes result from the β cell deficiency of the pancreatic cells, resulting in insufficient insulin secretion." (PMID 26273667, 2015). "Specifically, we assessed changes in patients’ clinical measures and medication costs associated with the conversion from insulin glargine to insulin detemir for basal blood glucose control among veterans seeking care in the VA diagnosed with type 2 diabetes." (PMID 26120575, 2015). "A study also characterized novel mutations in ABCC8 and KCNJ11 in the Russian population, which were novel loci for susceptibility to both type II diabetes and altered insulin secretion." (PMID 25871929, 2015). "Leptin and Adiponectin, which are two major hormones produced by adipose tissue and associated with type 2 diabetes, normalize insulin action." (PMID 26699937, 2015). "High blood glucose levels, caused by an imbalance in plasma levels of insulin and glucagon, are characteristic of type 2 diabetes." (PMID 26198634, 2015). "For example, PPARγ activation results in anti-inflammatory and anabolic actions; hence, PPARγ agonists like rosiglitazone have been used in the management of type II diabetes, a disease caused by widespread resistance to insulin actions." (PMID 25714093, 2015). "Not only PPARG but CSNK2A1, MAPK10, and MTOR are known as T2D genes and participate on parts of T2D associated pathways such as type II diabetes mellitus, insulin signaling pathway, and Wnt signaling pathway in KEGG." (PMID 26043787, 2015). "TCF7L2 has been associated with fasting plasma insulin, with glucose levels in type 2 diabetes patients to some extent with BMI, and with adipogenesis." (PMID 26608632, 2015). "Insulin resistance and the resultant increase in insulin output by pancreatic beta cells are associated with several metabolic abnormalities and almost always precede the development of type 2 diabetes." (PMID 26240831, 2015). "It is interesting that only 4 fasting plasma markers (10- and 12-(Z,E)-HODE/LA, insulin, and leptin/adiponectin) were able predict the risk of type 2 diabetes." (PMID 26132231, 2015). "This review will take a journey through the past and summarise the debate about the occurrence of mitochondrial dysfunction and its possible role in causing decreased insulin action in obesity and type 2 diabetes." (PMID 25385852, 2015).